RN7SL675P (RNA, 7SL, cytoplasmic 675, pseudogene)
Gene: Miscellaneous RNA gene on chromosome 8 (69,922,751 to 69,923,047, reverse strand). Ensembl gene ENSG00000239580.
Homologues: Orthologues: chimpanzee Metazoa_SRP (99% identical), macaque Metazoa_SRP (95% identical). Paralogues in human: RN7SL2 (82% identical), RN7SL1 (82% identical), RN7SL3 (81% identical), RN7SL679P (81% identical), RN7SL14P (80% identical), RN7SL126P (80% identical), RN7SL709P (80% identical), RN7SL47P (79% identical), RN7SL792P (79% identical), RN7SL296P (78% identical), RN7SL30P (78% identical), RN7SL45P (78% identical), and 702 more.